FXR1 (FMR1 autosomal homolog 1)
Diseases named in the same sentence as FXR1 in open-access papers (continued):
Sharing a sentence is not in itself a finding about the gene and the disease.
Infertility (1 paper, 2024). "Downregulation or knockout of FXR1 has been associated with disrupted spermiogenesis, which is implicated in infertility." (PMID 39411484, 2024).
influenza infection (1 paper, 2016). "Other proteins such as FXR1 and ILF3 have known function during influenza infection, but have not been reported to interact with NS1." (PMID 27199973, 2016).
leukemia (1 paper, 2024). A malignant (clonal) hematologic disorder, involving hematopoietic stem cells and characterized by the presence of primitive or atypical myeloid or lymphoid cells in the bone marrow and the blood. "Also, the functions of the newly identified m6A reader proteins, such as PRRC2A/B and FXR1, in the context of leukemia remain largely unexplored." (PMID 39085650, 2024).
male infertility (1 paper, 2020). The inability of the male to effect fertilization of an ovum after a specified period of unprotected intercourse. "CFTR, mutations of which are associated with male infertility, might be coregulated by FXR1, HNRNPA1, MATR3, PABPC1, G3BP2, FMR1, and SRSF7." (PMID 32316190, 2020). "EGFR, the signalling dysfunction of which was associated with human male infertility, might be coregulated by FXR1, FXR2, and HNRNPA1 (all of these three bind EGFR from CLIP experiments), G3BP2, G3BP1, FMR1, and SRSF7." (PMID 32316190, 2020).
meningioma (1 paper, 2026). A generally slow growing tumor attached to the dura mater. "Here we show that sex hormone interaction with PGRMC1, a transmembrane progesterone binding protein, regulates the activity of RNA processing proteins FXR1 and RBM39 to drive meningioma sex differences." (PMID 42282014, 2026).
Miscarriage (1 paper, 2022). A pregnancy that ends at a stage in which the fetus is incapable of surviving on its own, defined as the spontaneous loss of a fetus before the 22th week of pregnancy. "In our previous study, we explored that FXR1 mRNA expression levels were significantly decreased in trophoblasts from recurrent miscarriage patients and that FXR1 may be involved in the regulation of maternal fetal interface by binding to the 3′-UTR region of COX-2 to represses its expression." (PMID 34291416, 2022). "Our previous study showed that FXR1 expression was significantly decreased in trophoblasts from patients with unexplained recurrent spontaneous abortion (RSA); however, the role of FXR1 in trophoblast function during early placenta development has not been fully elucidated." (PMID 34291416, 2022).
Nephroblastoma (1 paper, 2023). An embryonal neoplasm characterized by the presence of epithelial, mesenchymal, and blastema components. "Inhibition of FXR1 may induce terminal differentiation of nephroblastoma." (PMID 38050239, 2023).
Obesity (1 paper, 2023). Accumulation of substantial excess body fat. "FXR1, NFKB1, and BACH1 are potent regulators of obesity-driven inflammation and metabolic dysfunction." (PMID 37698918, 2023).
osteosarcoma (1 paper, 2021). A usually aggressive malignant bone-forming mesenchymal neoplasm, predominantly affecting adolescents and young adults. "siRNAs were synthesized to separately silence the three genes, G3BP1, FUBP1, and FXR1, and the sensitivity of osteosarcoma cells to lobaplatin were detected." (PMID 33791202, 2021).
papilloma (1 paper, 2017). A benign epithelial neoplasm that projects above the surrounding epithelial surface and consists of villous or arborescent outgrowths of fibrovascular stroma. "IHC revealed elevated Fxr1 in normal tissues from Fbxo4−/− and + /− mice relative to that in Fbxo4 + / + mice; an obvious elevation of Fxr1 was noted in papilloma of Fbxo4 + /− and −/− mice compared to that in + / + mice." (PMID 29142209, 2017). "Five papilloma plus the adjacent normal tissues were randomly selected for Fxr1 IHC staining from these cohorts." (PMID 29142209, 2017).
post-traumatic stress disorder (1 paper, 2024). An anxiety disorder precipitated by an experience of intense fear or horror while exposed to a traumatic (especially life-threatening) event. "More intriguingly, RBP fragile X-related protein 1 (FXR1) was indicated to interact with miR-132 to regulate post-traumatic stress disorder (PTSD)-like behaviors after some traumatic mental stress." (PMID 39764416, 2024).
scleroderma (1 paper, 2002). Scleroderma is a rare autoimmune connective tissue disorder characterized by abnormal hardening of the skin and, sometimes, other organs. "A further gene – FXR1 is autoantigen known to elicit antibody production in scleroderma patients." (PMID 12087473, 2002).
virus infection (1 paper, 2018). "We observed a slight increase in virus infection rate for FXR1 depletion while FXR2 knockdown significantly reduced infection." (PMID 30511641, 2018).
ZIKV infection (1 paper, 2018). "We additionally tested the effect of FXR1 and FXR2 knockdown on ZIKV infection." (PMID 30511641, 2018).
cancer (40 papers, 2014 to 2026). A tumor composed of atypical neoplastic, often pleomorphic cells that invade other tissues. "FXR1 dysregulation and mutations are associated with several disease pathogenesis, including cancer." (PMID 38238286, 2024). "This now becomes obvious that FXR1 is dysregulated in various types of cancers, affecting the production and functioning of cancer-causing and tumor-suppressor proteins." (PMID 38238286, 2024). "Alteration in FXR1 expression or localization has been linked to the mRNAs of cancer suppressor genes, cancer-causing genes, and genes involved in genomic expression stability." (PMID 38238286, 2024). "FXR1 dysregulation has been implicated in diverse cancer types, suggesting its diagnostic and therapeutic potential." (PMID 38238286, 2024). "For instance, FXR1 is significantly overexpressed in the majority of cancers and is linked to an aggressive phenotype or a bad prognosis." (PMID 38238286, 2024). "Several studies have discovered that FXR1 overexpression at both the RNA and protein levels is strongly associated with a poor prognosis in several cancers." (PMID 38238286, 2024). "While analyzing the RNA-seq data of FXR1 knockdown, we observed changes in multiple pathways associated with cancer." (PMID 38709899, 2024). "Changes in FXR1 interaction with RNA networks have been linked to the emergence of cancer, although the theoretical framework defining these alterations in interaction is insufficient." (PMID 38238286, 2024). "This altered FXR1 activity seems to be present in all cancer types, and it appears to be associated with the dysregulation of the corresponding mRNA targets." (PMID 38238286, 2024). "Overexpression of FXR1 was associated with poorer prognostic outcomes in most cancers, while it was linked to a better prognosis in GBM, LAML, and READ." (PMID 38050239, 2023). "A correlation was found between FXR1 expression and immune infiltration by cancer-associated fibroblasts in specific tumors." (PMID 38050239, 2023). "FXR1 has the potential to serve as a diagnostic and prognostic biomarker for cancer, with therapeutic value in immune-based, targeted, or cytotoxic treatments." (PMID 38050239, 2023). "The diagnostic efficacy of FXR1 across diverse tumor types was assessed using ROC curves in a cohort of 33 different cancers." (PMID 38050239, 2023). "Among them, TNRC6, DGCR8, C17ORF85, ZC3H7B, SFRS1 and TIA1, were obviously positively associated with XIST in ≥3 cancers; while eIF4AIII, FXR1, FXR2 and C22ORF28 were significantly negatively correlated with XIST in ≥3 cancers." (PMID 36212008, 2022). "Nevertheless, the function of FXR1 in cancer and the underlying molecular mechanisms remain elusive." (PMID 28767039, 2017). "Consistent with a substrate relationship, Fxr1 is overexpressed in Fbxo4 knockout cells, tissues and in human cancer cells, harbouring inactivating Fbxo4 mutations." (PMID 29142209, 2017). "We have found that a single point mutation in U2AF1 that is recurrent in multiple human cancers alters this kinetic balance to favor post-transcriptional splicing of both the β-globin reporter and also endogenous FXR1 mRNAs." (PMID 25271374, 2014). "Since most, if not all, patients share similar disease processes, dysregulated expression and/or function of the FXR1 may constitute a pathogenic event in cancer." (PMID 38238286, 2024). "Therefore, establishing the connection between FXR1 and the microtubule-associated gene network would reveal the crucial role of FXR1 in cancer cells." (PMID 38709899, 2024). "Therefore, it is more probable that loss of function and/or expression of FXR1 in cancer reflect one of the several “hits” required for cancer development." (PMID 38238286, 2024). "Consequently, these findings underscore the robust diagnostic potential of FXR1 across various cancer types." (PMID 38050239, 2023).
cancer (continued). "Moreover, we observed a statistically positive correlation between FXR1 expression and the estimated infiltration value of cancer-associated fibroblasts in COAD, ESCA, HNSC, KIRC, PAAD and STAD but noted a negative correlation for SARC and TGCT." (PMID 38050239, 2023). "The findings demonstrate that FXR1 could play a significant prognostic and diagnostic role in a wide range of cancers and its multifaceted role in cancer regulation." (PMID 38050239, 2023). "However, the underlying mechanism of FXR1 regulation in oncogenesis tends to be complex and varies among various types of cancer." (PMID 35194031, 2022). "While increased expression of FXR1 in cancer has been linked to senescence evasion and consequently tumor initiation and progression, decreased expression of FXPs in neurodegeneration may contribute to pathogenic protein aggregation and death of vulnerable neurons." (PMID 41117937, 2025). "Collectively, our data establishes FXR1 as an important regulator of oncogenic processes in cancer tissues and serves as a therapeutic liability." (PMID 41932914, 2026). "FXR1 is a key regulator of the translation of multiple oncogenes and therefore represents a vulnerable target for cancer therapy." (PMID 41932914, 2026). "Fragile X-related protein 1 (FXR1) is highly amplified and overexpressed in ovarian and several other cancers." (PMID 41932914, 2026). "Several cancer-related genes are up/downregulated by FXR1 by modulating post-transcriptional and translational gene expression levels." (PMID 38238286, 2024). "For the first time, here we report, FXR1 is arginine methylated and the functional consequence of methylation relating to RNA binding activity in cancer cells." (PMID 38709899, 2024). "For example, a single missense mutation (Ser34Phe) in the zinc finger domain of the conserved splicing factor U2AF1 is common in different types of cancers, leading to the post-transcriptional splicing of β-globin and FXR1 mRNAs." (PMID 38763947, 2024). "This suggests that FXR1 can bind to and stabilize these transcripts, hence possibly promoting the growth and proliferation of cancer cells." (PMID 38709899, 2024). "As a result, we argue that FXR1 methylation increases its G4-RNA-binding capacity, which promotes cancer cell growth and proliferation." (PMID 38709899, 2024). "Because of these properties, EVs are important carriers to target FXR1 for cancer treatment and diagnostics." (PMID 38238286, 2024). "In particular, FXR1-mediated gene regulation involves in several cellular phenomena related to cancer growth, metastasis, epithelial-mesenchymal transition, senescence, apoptosis, and angiogenesis." (PMID 38238286, 2024). "The contrasting roles of FXR1 in mRNA stability and destabilization considering the G4-structural features need to be investigated further in cancer cells." (PMID 38709899, 2024). "Our findings also show that PRMT5 directly adds a dimethyl group to FXR1 arginine residues in cancer cells." (PMID 38709899, 2024). "Our data also show that FXR1 targets the coding regions, 5′UTR, and 3′UTR of key genes involved in microtubule filaments, potentially linked to cancer progression." (PMID 38709899, 2024). "Next, we investigated the capacity of PRMT5/1i to inhibit FXR1 mRNA transcript and protein levels in cancer cells." (PMID 38709899, 2024). "RBP, Fragile X mental retardation protein-1 (FXR1), is a chromosome 3q amplification gene overexpressed in multiple cancers and exerts oncogenic signaling to promote tumorigenesis." (PMID 38709899, 2024). "This review highlights the current knowledge of FXR1 expression and function in various cancer situations, emphasizing its functional variety and complexity." (PMID 38238286, 2024). "To interrogate the oncogenic functions and gene signatures essential for cancer cell growth and proliferation, we performed an RNA-seq by silencing FXR1 and PRMT5 separately using shRNAs and analyzed the high-throughput sequencing data." (PMID 38709899, 2024).
cancer (continued). "We further address the challenges and opportunities of targeting FXR1 for cancer diagnosis and treatment and propose future directions for FXR1 research in oncology." (PMID 38238286, 2024). "Here, we report that post-translational modification of FXR1 enhances the binding with mRNAs and is involved in cancer cell growth and proliferation." (PMID 38709899, 2024). "An alternative way of thinking about FXR1 roles in cancer is to divide them into different categories: prolonged proliferative potential, evading cell death and senescence." (PMID 38238286, 2024). "FXR1 and miR301a-3p are upregulated in NSLSC and HNSCC cancers, suggesting a distinct regulatory mechanism for miR301a-3p stabilization by FXR1." (PMID 38238286, 2024). "Further experimental strategies are needed to determine if FXR1 binds to non-G4 RNAs and acts as a repressor or promoter of their mRNA turnover and translation in cancer cells." (PMID 38709899, 2024). "This work intends to provide an in-depth review of FXR1 as an emerging oncotarget with multiple roles and implications in cancer biology and therapy." (PMID 38238286, 2024). "FXR1 is an attractive target for cancer treatment due to its widespread expression in nearly all cancers and its important function in the post-transcriptional controls of key genes involved in tumor growth and survival." (PMID 38238286, 2024). "Therefore, deciphering the intricate relationships between FXR1 and its RNA targets associated with cancer could help improve our understanding of tumor development and possibly lead to the discovery of novel targets for cancer therapy." (PMID 38238286, 2024). "In conclusion, we must gain a deeper understanding of FXR1 in cancers because they indicate great promise as potential therapeutic targets in the foreseeable future for cancer treatment." (PMID 38238286, 2024). "Our findings suggest that PRMT5-mediated FXR1 methylation is required for RNA/G4-RNA binding, which promotes gene expression in cancer cells." (PMID 38709899, 2024). "Studies have shown that FXR1 plays an important role in cancer cell proliferation, invasion and migration and is differentially expressed in cancers." (PMID 38050239, 2023). "In order to clarify the expression of FXR1 in pan-cancer, the FXR1 mRNA-expression levels in the TCGA and GTEx databases were analyzed." (PMID 38050239, 2023). "Despite the growing body of research on the connection between FXR1 and cancer, there is a scarcity of comprehensive pan-cancer analyses focusing on FXR1." (PMID 38050239, 2023). "In summary, this research comprehensively analyzed FXR1 across various types of cancer, revealing significant correlations between FXR1 expression and clinical prognosis, mutation, and immune cell infiltration." (PMID 38050239, 2023). "This study aimed to gain a comprehensive and systematic understanding of the analysis of FXR1’s role in cancers." (PMID 38050239, 2023). "We investigated the relationship between FXR1 expression and the diverse molecular and immune subtypes across various cancer types, utilizing the TISIDB database." (PMID 38050239, 2023). "A differential expression analysis of FXR1 was performed in the cancers where FXR1 can negatively affect prognosis in order to determine the biological value of FXR1 expression in various tumor tissues." (PMID 38050239, 2023). "This analysis revealed 10 central hub genes, establishing a strong correlation between their expression and FXR1 in various cancer types." (PMID 38050239, 2023). "Our study provides insights into the role of FXR1 in promoting, inhibiting, and treating diverse cancers." (PMID 38050239, 2023). "This study examined the relationship between FXR1 and the immune microenvironment in pan-cancer using the GEPIA2 database." (PMID 38050239, 2023). "The genomic alterations affecting the expression of FXR1 in various cancer types were assessed by leveraging the cBioPortal online tool." (PMID 38050239, 2023).